RNU2-56P (RNA, U2 small nuclear 56, pseudogene)
Gene: Small nuclear RNA gene on chromosome 20 (18,265,690 to 18,265,879, reverse strand). Ensembl gene ENSG00000252635.
Homologues: Orthologues: chimpanzee U2 (99% identical), macaque U2 (91% identical), dog U2 (86% identical), pig U2 (78% identical), guinea pig U2 (75% identical), rabbit U2 (72% identical), rabbit U2 (42% identical), rabbit U2 (39% identical), tropical clawed frog U2 (22% identical). Paralogues in human: RNU2-61P (86% identical), U2 (85% identical), U2 (83% identical), RNU2-2 (82% identical), RNU2-48P (82% identical), RNU2-3P (81% identical), RNU2-6P (81% identical), RNU2-59P (80% identical), RNU2-64P (80% identical), RNU2-14P (79% identical), RNU2-52P (79% identical), RNU2-4P (79% identical), and 65 more.